EN2 (engrailed homeobox 2)
Diseases named in the same sentence as EN2 in open-access papers (continued):
Sharing a sentence is not in itself a finding about the gene and the disease.
tumor (continued). "Similar work on human tumour samples was vital to draw more comprehensive conclusions regarding EN2 expression in EOC." (PMID 30285763, 2018). "En2 expression was higher in platinum-resistant tumours compared to those that were platinum-sensitive, particularly when considering those patients who had already received some chemotherapy prior to surgery, i.e. the interval surgery cohort; p = 0.0232)." (PMID 30285763, 2018). "The relative expression of En2 in normal ovary was very low in comparison to that of the malignant tumour samples." (PMID 30285763, 2018). "Additionally, we performed further analysis of the xenograft GBM tumour tissues using HE and immunohistochemistry staining, which revealed that the expression of Ki‐67 and EN2 in the tumour tissues was observably reduced." (PMID 40889210, 2025). "Recent studies have shown that the EN2 gene may play an important role in the proliferation and migration of tumor cells." (PMID 39607581, 2025). "Furthermore, we performed IHC staining on the xenograft GBM tumour tissues for further analysis, which revealed that TMZ treatment observably suppressed the expression of Ki‐67 after the silence of EN2, indicating a significant reduction in tumour growth." (PMID 40889210, 2025). "As anticipated, EN2 expression was significantly elevated in GBM tumour tissues." (PMID 40889210, 2025). "In conclusion, overexpression of EN2 in EC tissue may play an important role in tumor invasion and progression." (PMID 39607581, 2025). "Therefore, our results highlight the potential of EN2 as an important therapeutic target for regulating tumour metabolism, providing new strategies to overcome drug resistance and develop combination therapies." (PMID 40889210, 2025). "Very recently, EN2 was reported to play an oncogenic role in tumor progression via CCL20 in CRC43." (PMID 35169223, 2022). "Immunohistochemistry indicated that compared with the group miR-NC+EN2-NC, miR-27b-3p up-regulation significantly down-regulated the expression of EN2 protein in xenograft tumours, while EN2 re-introduction (the group miR-27b-OE+EN2-OE) reversed the inhibitory effects of miR-27b-3p on EN2." (PMID 33350453, 2021). "We generated a shRNA lentiviral vector specifically directed against the SPARC transcript to determine whether the EN2-mediated tumor proliferation, migration and invasion are dependent on SPARC expression." (PMID 32117645, 2020). "Previous research has shown the abnormal expression of EN2 in a wide variety of tumor." (PMID 32732864, 2020). "Our findings indicate that EN2 secretion by tumors may be a means of preventing viral-mediated immune invasion of tissue immediately adjacent to the tumor." (PMID 30914795, 2019). "We hypothesised that over-expression of En2 mRNA and EN2 protein in human EOC tumours, may prove useful as a diagnostic, prognostic or treatment response biomarker, helping to influence treatment decisions, and ultimately improve overall survival rates." (PMID 30285763, 2018). "EN2 over-expression has been identified in a number of adult human cancers, namely breast, prostate, and bladder, and appears to have a functional role in tumour development." (PMID 30285763, 2018). "Taken together, it is plausible that deregulated expression of PAX2 and EN2 may ultimately promote tumor progression specifically via cancer cell proliferation and survival." (PMID 21566742, 2008). "Importantly, our animal experiments indicated that knocking down EN2 in tumour tissues could observably enhance tumour resistance." (PMID 40889210, 2025). "Moreover, EN2 exerts a carcinogenic or tumor-suppressive role in different cancers." (PMID 33685351, 2021). "Also, the results of IHC revealed that there was the correlation between EN2 and the tumor size, suggesting that EN2 might be involved in the regulation of proliferation." (PMID 32732864, 2020).
tumor (continued). "These reasons prompted us to explore herein the putative tumorigenic role of secreted EN2 protein in normal and tumor prostate cells, inasmuch as this information could pave the way towards the identification and development of novel therapeutic avenues in PCa." (PMID 31500112, 2019). "In addition, we demonstrate herein, for the first time, that secreted EN2 protein could act as a tumorigenic factor in normal and tumor prostate cells, by modulating key functional parameters and signaling pathways." (PMID 31500112, 2019). "To further investigate the expression of EN2 in GBM tissues and its potential clinical significance, we conducted a systematic analysis of EN2 expression in GBM tumour tissues using both the TCGA and GEO databases." (PMID 40889210, 2025). "In silico analysis uncovered three putative miRNA targets in humans, namely the transcription factor 7 (TCF7), nuclear receptor coactivator 6 (NCoA6), and engrailed-2 (EN2), all upregulated in BC and exploiting their role in tumor initiation and progression." (PMID 39519491, 2024). "We identified cohort-specific DNA methylation markers in the CpG islands of PDX1, EN2, and MSX1 and validated tumor-specific hypermethylation levels of these three genes via optimized qMSP methods with highly sensitive primer sets." (PMID 35169223, 2022). "To further explore the drug resistance of GBM cells with the silence of EN2 in vivo, we subcutaneously implanted GBM cell‐shNC and GBM cell‐shEN2 into nude mice and administered TMZ treatment, regularly monitoring the size of the tumour." (PMID 40889210, 2025). "Mechanistically, EN2 activates the expression of Sterol Regulatory Element‐Binding Protein 1 (SREBP1), thereby enhancing the fatty acid synthesis metabolic pathway and contributing to tumour resistance." (PMID 40889210, 2025). "By examining the differences in the methylation levels observed in tumors and adjacent healthy tissues via hybrid capture-based targeted bisulfite sequencing, we discovered significantly hypermethylated intragenic CGI regions in PDX1, EN2, and MSX1 in the tumor samples." (PMID 35169223, 2022). "To further verify the effect of EN2 on tumorigenesis in vivo, we established the subcutaneous xenograft tumor models using SW480 cells with or without EN2 knockdown." (PMID 32732864, 2020). "Patients with HGSOC tumours staining positive for EN2 had a significantly shorter median PFS than those with EN2 negative tumours (10 vs 17.5 months; p = 0.0103)." (PMID 30285763, 2018). "We demonstrated that EN2 protein was located in the cytoplasm of EOC cell lines and tumour tissue, and not the nucleus, as seen in normal adult Purkinje neurones." (PMID 30285763, 2018).
cancer (18 papers, 2008 to 2025). A tumor composed of atypical neoplastic, often pleomorphic cells that invade other tissues. "Multiple studies have indicated that EN2 is highly expressed in various cancer cells and tissues and is associated with the occurrence and progression of different cancers." (PMID 40889210, 2025). "We analyzed the enriched KEGG pathway associations of EN2 and EN2 treated with Selitrectinib, while EN2 interactome is associated with many cancer-related pathways, almost all these associations are lost after treatment with Selitrectinib." (PMID 37686522, 2023). "Notably, EN2 interacted with the eukaryotic initiation factor eIF-4E2, which is associated with translation under hypoxic conditions and is exploited in cancer." (PMID 37686522, 2023). "When cancer cells in their dormant phase absorb these EN2 proteins, they are reactivated, changed in shape, or fused together." (PMID 39607581, 2025). "A recent study showed that EN2 protein can be secreted from cancer cells and taken up by other cells, providing a typical example of this phenomenon." (PMID 39607581, 2025). "The level of EN2 detected using RT-PCR in carcinoma was higher than that in para-carcinoma, and the level in para-carcinoma was higher than that in the cervical endometrium (P < 0.05)." (PMID 39607581, 2025). "EN2 protein detected using RT-PCR in carcinoma was higher than that in benign controls (P = 0.0357)." (PMID 39607581, 2025). "RT-PCR indicated that EN2 expression in the carcinoma was much higher than in para-carcinoma tissues (P = 0.019)." (PMID 39607581, 2025). "Homeobox genes have emerged as key players in the development of cancer so understanding the function of EN2 in ESCC is of great interest." (PMID 32117645, 2020). "Engrailed-2 (EN2), a member of the engrailed homeobox family, has been shown to be abnormally expressed in a variety of cancers." (PMID 32732864, 2020). "We found that the expression of EN2 was enough to distinguish CRC cancer patients’ tissues from normal ones." (PMID 32732864, 2020). "In order to understand more about the role of EN2 in cancer, we began by studying its expression in cells lines derived from tumors and normal tissue." (PMID 30914795, 2019). "Our findings indicate that EN2 protein can be secreted from cancer cells via microvesicles and that it can be taken up by other, non-EN2 expressing cells." (PMID 30914795, 2019). "Although higher than the normal specimens, the En2 expression in benign and borderline epithelial tumours was also much lower than the malignant tumours." (PMID 30285763, 2018). "EN2 appeared to be predominantly expressed within the cytoplasm of the cancer cell lines, especially after the cells were permeabilised." (PMID 30285763, 2018). "Engrailed-2 (EN2) is a homeodomain-containing transcription factor, essential during embryological neural development, which is dysregulated in several cancer types." (PMID 30285763, 2018). "This further implicates En-2 as a therapeutic target for cancer either directly or indirectly via targeting PAX2." (PMID 21566742, 2008). "Notably, transcriptomic sequencing results from GBM cells with the silence of EN2 showed a significant activation of the fatty acid synthesis metabolic pathway in cancer cells." (PMID 40889210, 2025). "This indicates that EN2 plays an important role in cancer occurrence and progression, but its main mechanisms of action in GBM remain unclear." (PMID 40889210, 2025). "Because the expression and characteristic of EN2 could change due to the change of cell proliferation, EN2 could be secreted into the cytoplasm and even extracellular in cancer cells." (PMID 32539763, 2020). "Engrailed-2 (EN2) is a homeodomain-containing transcription factor that has roles in boundary formation and neural guidance in early development, but which is also expressed in a range of cancers." (PMID 30914795, 2019).
cancer (continued). "To validate the important role of SREBP1 in fatty acid synthesis in cancer cells, we found that the triglyceride content observably decreased in GBM cells whose EN2 was knocked down." (PMID 40889210, 2025). "In this study, we demonstrate that EN2 can promote GBM progression in vitro and in vivo, thereby activating fatty acid metabolism in cancer cells." (PMID 40889210, 2025). "Recently published studies dedicated to other potential urinary protein biomarkers have shown that levels of some of them (EN2, αHGF, IGFBP3, ZAG) are elevated in PCa, while the urinary ANXA3, PAP, and PSA have inverse relationship with cancer." (PMID 33791193, 2020). "EN2 is dysregulated in several cancer types, but at present there is no published data on its presence in EOC." (PMID 30285763, 2018). "Additionally, EN2 was remarkably overexpressed in CRC tissues relative to normal tissues adjacent to cancer." (PMID 33685351, 2021). "Carcinoma tissue was confirmed in the PC samples and no carcinoma tissue was confirmed in the BPH samples by the pathologists and EN2 was mainly expressed in glandular and/or carcinoma cells." (PMID 32539763, 2020).
benign tumours (1 paper, 2018). "Positive cytoplasmic EN2 staining was demonstrated in 78% of EOCs and over 65% of borderline tumours, whilst there was no staining in the majority of benign tumours and in all normal ovary specimens." (PMID 30285763, 2018). "EN2 protein staining was also detected in the majority of EOC and borderline tumour specimens, and was negative in all normal ovary specimens, and in most benign tumours." (PMID 30285763, 2018).
brain diseases (1 paper, 2018). "Conversely, although these EN2 related anomalies might represent a predisposition to develop brain diseases, our results did not support direct relationship between EN2 mutations and specific clinical phenotypes." (PMID 30147646, 2018).
prostate (1 paper, 2008). "Collectively, our data suggest that En-2 may prove useful as a specific biomarker marker of prostate malignancy and further investigation may explain its mechanistic contribution to the tumorigenic process." (PMID 21566742, 2008).
psychiatric disorder (1 paper, 2012). A disorder characterized by behavioral and/or psychological abnormalities, often accompanied by physical symptoms. "Mice with a deletion in En2 may represent an informative model for understanding how neurodevelopmental defects can lead to neuroanatomical or neurochemical disruptions that directly or indirectly impact behaviors relevant to psychiatric disorders." (PMID 22829897, 2012).
EN2 also shares sentences with these, for which no sentence is quoted: Anxiety (2 papers); lung carcinoma (2); schizophrenia (2); acute lymphoblastic leukemia (1); brain glioblastoma (1); chronic eosinophilic leukemia (1); colon cancer (1); congenital fibrosarcoma (1); congenital mesoblastic nephroma (1); genetic disorder (1); infection (1); inflammatory myofibroblastic tumor (1); insulinoma (1); Lesch-Nyhan disease (1); microcephaly (1); neuroblastoma (1); non-small cell lung carcinoma (1); promyelocytic leukemia (1); renal cell carcinoma (1); renal failure (1); sarcopenia (1); stem cell leukemia (1); Wilms tumor (1).